MMP9 (matrix metallopeptidase 9)
Diseases named in the same sentence as MMP9 in open-access papers (continued):
Sharing a sentence is not in itself a finding about the gene and the disease.
periodontitis (continued). "In addition, there was a significant association between MMP-9 -1562C>T polymorphism and periodontitis under the recessive model (TT vs. TC+CC: OR=2.585, 95% C=1.177–5.678, P=0.018) in the AgP group." (PMID 31497543, 2019). "In particular MMP8 and MMP9 in gingival fluid have been shown to be associated with periodontitis." (PMID 26656474, 2015). "Furthermore, it was investigated whether possible confounders could mediate associations between MMP-9, periodontitis, and CVD." (PMID 33810003, 2021). "In this regard, periodontitis has been closely related to high levels of NO, so it is possible to hypothesize a close correlation between NO, MMP-9, and periodontitis, which, when associated with CVD, maybe a significant risk factor to the development of negative CVD outcomes." (PMID 33810003, 2021). "Thus, we performed the current systematic and meta-analysis of all available case-control studies to provide more precise estimation of the association of MMP-2 -753C>T (rs2285053) and MMP-9 -1562C>T (rs3918242) polymorphisms with chronic/aggressive periodontitis susceptibility." (PMID 31497543, 2019). "Therefore, we hypothesize that there was an association between the polymorphisms in the IL12B, IL18, and MMP9 regions and the development of periodontitis." (PMID 31065235, 2019). "However, both MMP-2 -753C>T and MMP-9 -1562C>T polymorphisms might have influence on the susceptibility of periodontitis by ethnicity background." (PMID 31497543, 2019). "Therefore, both MMP-2 -753C>T and MMP-9 -1562C>T polymorphisms might have influence on the susceptibility of periodontitis by ethnicity background." (PMID 31497543, 2019). "However, MMP-2-753C>T and MMP-9-1562C>T polymorphisms might have influence on the susceptibility of periodontitis by ethnicity." (PMID 31497543, 2019). "Currently, MMP-8 in oral fluids is a highly utilized marker in diagnosing periodontitis, while salivary MMP-9 serves as a marker of inflammatory status." (PMID 40243433, 2025). "Lastly, the host enzymes MMP-1 and MMP-9 were statistically significantly (p ≤ 0.003) increased at both periodontitis versus gingivitis sites and gingivitis versus healthy sites." (PMID 41303313, 2025). "MMP9 levels were significantly elevated in both gingivitis and periodontitis compared to healthy sites, with a p-value of ≤0.001." (PMID 41303313, 2025). "MMP-13, a collagenase found in fibroblasts, macrophages, osteoblasts, plasma cells, and gingival epithelial cells, is implicated in the destruction of periodontal soft tissue and, together with MMP-9, in bone resorption in periodontitis." (PMID 40243433, 2025). "MMP-2, MMP-8, MMP-9, and MMP-20 have been implicated in caries-induced dentine matrix destruction, as well as in periodontitis." (PMID 40332093, 2025). "For example, in the OM, pathogens like Prevotella intermedia and Fusobacterium nucleatum induce the expression of MMP-1, MMP-8, and MMP-9 during periodontitis and dental caries." (PMID 40332093, 2025). "Another MMP present in the progression of inflammation in patients with periodontitis is MMP-9, which degrades collagen types IV, V, and XI, as well as proteoglycans and elastin." (PMID 41002732, 2025). "Exenatide downregulates IL-1β, inducible nitric oxide synthase (iNOS), and MMP-9 transcription in gingival tissues with periodontitis." (PMID 41328144, 2025). "Certain bacteria in subgingival plaques appear to be minimally affected by the factors associated with gingivitis and periodontitis, despite most bacteria exhibiting correlations with IL-1β, endotoxins, TLR-SEAP, TLR-ATP, PAD, MMP-1, MMP-9, GBI, and MGI." (PMID 41303313, 2025). "The hypermethylation of MMPs, such as MMP-9, has been shown to enhance this activity, making it a key factor in chronic and severe periodontitis." (PMID 40243433, 2025). "MMP-8 and MMP-9, as the main collagenolytic enzymes in saliva and gingival crevicular fluid, are responsible for collagen degradation in gingivitis and periodontitis." (PMID 39684335, 2024).
periodontitis (continued). "Another study stated that (MMP-9), is related to the degradation of collagen and gelatin in the gingival crevicular fluid and is distinctly elevated in periodontitis." (PMID 39350180, 2024). "Higher levels of MMP-9 were quantified in the saliva of patients with earlier stages of periodontitis (localised periodontitis), compared to later stages (generalised periodontitis)." (PMID 39450334, 2024). "Increased plasma levels of IL-1β, IL-6, TNF-α, CRP, MMP-8, and MMP-9 have been observed in patients with periodontitis." (PMID 38672972, 2024). "It was shown that MMP-9 presence is positively correlated with periodontitis severity, which decreases when treated." (PMID 38474009, 2024). "Increased MMP-9 levels are a distinct feature of progressive periodontitis and are mainly produced by neutrophils and macrophages being continually recruited to the periodontal lesion." (PMID 39064296, 2024). "Authors reported that the levels of MMP-9 in DM patients with chronic periodontitis were nearly doubled (156.95 ± 29.80 ng/mL) compared to the values in the control group (74.96 ± 6.32 ng/mL) (P < .001)." (PMID 38614881, 2024). "The main source of MMP-9 is PMNs, detected during advanced periodontitis in the JE, the SE, and as a scattered deposit along connective tissues of periodontitis-affected gingival tissues, with a lower level in the epithelium not exposed to inflammation." (PMID 38474009, 2024). "Combination therapy decreases the release of virulence factors and MMP-9, thus indirectly restoring the imbalance in the host inflammatory response and resulting in a synergistic effect against periodontitis." (PMID 38779565, 2024). "It was also found that levels of MMP-9 are increased in patients with periodontitis and decrease after periodontal therapy." (PMID 39200004, 2024). "MMP-9 modulates the extracellular matrix in periodontal tissue, and its selective expression can contribute to the acceleration of matrix degradation in periodontitis and other pathological conditions." (PMID 38193137, 2024). "Another study found a positive correlation between periodontal pocket depth and MMP-9 concentration in patients with moderate or severe periodontitis, and also between the concentration of MMP-9 in the oral fluid and the number of affected teeth." (PMID 37959214, 2023). "Administration of butyrate (5 mM) resulted in increased NADPH-related oxidative stress and inflammation, presumably mediated by MMP-9, in a rat model of periodontitis." (PMID 37893122, 2023). "In chronic periodontitis patients, MMP-9 can readily digest denatured collagen, gelatin, and other extracellular matrix elements." (PMID 36661522, 2023). "This study’s objective was to investigate and compare the levels of MMPs (MMP8 and MMP9) in individuals with DS who have periodontitis (experimental group) to systemically healthy individuals with and without periodontitis (control groups)." (PMID 37448427, 2023). "A meta-analysis also showed statistically significant differences in MMP-9 levels in serum and gingival crevicular fluid between patients with periodontitis and periodontally healthy individuals." (PMID 37959214, 2023). "In this study, we assessed MMP8 (collagenase 2) and MMP9 (gelatinase b) levels in DS individuals with chronic periodontitis to further confirm the release of pro-inflammatory cytokines by specific microorganisms." (PMID 37448427, 2023). "The high expression of MMP-8 and MMP-9 in chronic periodontitis accurately reflects the patient’s condition and therefore can be used as a biomarker for the diagnosis of periodontitis." (PMID 36923589, 2023). "The mean differences in MMP8 and MMP9 in the DS group with chronic periodontitis showed highly statistically significant levels compared to both systemically healthy groups." (PMID 37448427, 2023). "The main source of MMP-9 is the polymorphonuclear neutrophils, with high levels being expressed in inflamed junctional and gingival epithelial cells in advanced periodontitis." (PMID 35163727, 2022).
periodontitis (continued). "Salivary biomarkers (MMP-8, MMP-9, and TIMP-1) exhibited a high diagnostic accuracy in discriminating between periodontal health from periodontitis in general and S1 periodontitis." (PMID 36292174, 2022). "The MMP-9 levels for subjects with both type-II DM and chronic periodontitis came out to be 32.8 ± 11.1 ng/dL in another study." (PMID 35408573, 2022). "Our results also depict an almost two-fold increase in the MMP-9 levels of type-II DM subjects with chronic periodontitis compared to the control group." (PMID 35408573, 2022). "There was an almost two-fold increase in the average salivary MMP-9 levels of chronic periodontitis patients with type-II DM compared to the chronic periodontitis patients alone." (PMID 35408573, 2022). "A similar study conducted on gingival crevicular fluid (GCF) samples instead of saliva concluded the MMP-9 levels to be 17.1 ± 1.7 ng/dL for subjects with chronic periodontitis." (PMID 35408573, 2022). "At the periodontal level, MMP-9 is mainly synthesized by neutrophils in the presence of inflammation, and a higher number of oral neutrophils were detected in periodontitis patients in relation to healthy control." (PMID 36077255, 2022). "GCF levels of MMP-9 and -13 have been suggested as useful biomarkers for the progression of periodontitis in patients with moderate chronic periodontitis who have active sites and who have been observed for 2 months." (PMID 35163727, 2022). "Previously, MMP-9 in saliva showed a 0.67 area under the ROC curve for the detection of periodontitis." (PMID 36077255, 2022). "Among others, metalloproteinases for which the relationship between gene polymorphisms and the occurrence of periodontitis was evaluated are MMP-2 and MMP-9." (PMID 35454140, 2022). "Since MMP-9 activity increases in inflamed periodontitis sites and correlates with the severity of the disease, it was used as a model of MMP." (PMID 35784661, 2022). "This resulted in a further decrease in the MMP-9 levels in patients who received orthodontic treatment after periodontitis was improved or resolved." (PMID 33498206, 2021). "The ability of Synergoss Red to downregulate MMP-9 is notable; in fact, MMPs and in particular, MMP-9, are implicated in periodontal tissue destruction in chronic periodontitis." (PMID 34063147, 2021). "This analysis revealed that the levels of salivary MMP-8 and MMP-9 were significantly higher in the periodontitis subjects." (PMID 35048079, 2021). "The p for trend test evidenced that MMP-9 in both serum and saliva were gradually increased in healthy patients and in patients with periodontitis, CVD, and periodontitis + CVD (p-trend < 0.001)." (PMID 33810003, 2021). "The mean concentrations of MMP-8 and MMP-9 in the saliva from the periodontitis subjects were, respectively, 2.8 and 4.0 times higher than those in the saliva from the healthy subjects." (PMID 35048079, 2021). "For the study, the impact of MMP-9 of periodontitis and CVD on serum and saliva concentrations was analyzed." (PMID 33810003, 2021). "Metalloproteinase-9 (MMP-9), an enzyme that is involved in the degradation of gelatin and collagen and present in the gingival crevicular fluid, is markedly increased in periodontitis." (PMID 33498206, 2021). "MMP9 is involved in inflammation and tumor growth, including periodontitis and several types of cancer." (PMID 34577904, 2021). "Larger scale studies conducted on patients with various degrees of periodontitis and orthodontic treatments are needed to further establish the use of salivary MMP-9 as a predictor of inflammation following orthodontic treatment." (PMID 33498206, 2021). "On the other hand, a meta-analysis involving an excess of 6000 subjects suggested that MMP-9 reduced the risk of periodontitis, whereas MMP-3 and -8 increased the risk of periodontitis." (PMID 34444764, 2021).
periodontitis (continued). "MMP-9, which was found in higher concentration in saliva from periodontitis subjects in our study, has been reported to induce the breakdown of the intestinal epithelial barrier in a mouse model." (PMID 35048079, 2021). "This study found that CVD and periodontitis + CVD presented elevated MMP-9 levels in comparison to periodontitis patients and healthy subjects." (PMID 33810003, 2021). "For example, salivary as well as circulating MMP-8 and MMP-9 levels were significantly elevated in periodontitis patients and reduced after periodontal treatment." (PMID 33498206, 2021). "MMP-8 and MMP-9 have been frequently found to be elevated in chronic or advanced periodontitis, assessing the potential of these MMPs as the most promising periodontitis biomarkers." (PMID 33477537, 2021). "The results of the present study appear highly encouraging but need to be better validated by studies on a larger number of patients and with longitudinal design in order to better understand the upregulation of MMP-9 in patients with periodontitis and CVD." (PMID 33810003, 2021). "This study evidenced that patients with CVD and periodontitis + CVD presented elevated MMP-9 concentrations in serum and saliva compared to patients with periodontitis and healthy subjects." (PMID 33810003, 2021). "Since no impairment of epithelial barrier integrity was observed with the saliva samples from the periodontitis patients, this suggests that MMP-9 concentrations in the samples were either too low to have an effect or that the MMP-9 was in an inactive form." (PMID 35048079, 2021). "MMP-8 and MMP-9 were chosen for assessment in this study as they are the most common MMPs in periodontal tissues that indicate periodontitis progression, severity, and treatment response." (PMID 34444764, 2021). "MMP-9 is among the best studied proteinases when it comes to its role in periodontitis and its activation in infections." (PMID 33498206, 2021). "In another study, SPR method was utilized for matrixmetalloproteinase-9 (MMP-9) detection, which is of interest in chronic periodontitis (CP) disease." (PMID 34093888, 2021). "They reported significantly elevated levels of MMP-8 and MMP-9 in saliva from the periodontitis subjects compared with saliva from the healthy subjects." (PMID 35048079, 2021). "This study aimed to evaluate the association and effect of periodontitis and CVD on serum and salivary MMP-9 levels." (PMID 33810003, 2021). "In this regard, recent research has shown that patients with periodontitis had significantly high serum levels of MMP-9 and that good maintenance therapy resulted in a significant reduction in serum levels of MMP-9 in patients with coronary artery disease." (PMID 33810003, 2021). "For example, exenatide decreased the periodontitis-induced inflammatory gene expression of IL-1β, iNOS, and matrix metalloproteinase-9 (MMP-9) in the gingiva." (PMID 33274238, 2020). "Using a meta-analytical approach, a previous study found that MMP-8, MMP-9, IL-1β, IL-6, and Hb were salivary biomarkers with good capability to detect periodontitis in systemically healthy subjects." (PMID 33383828, 2020). "Using doxycycline dosage as SDD (sub antimicrobial dose doxycycline) for the treatment of periodontitis, Chouy etal., found that doxycycline reduced the MMP-9 concentration and increased TIMP-1 concentration." (PMID 33841538, 2020). "Increased levels of pro-inflammatory mediators such as interleukin-6 (IL-6), C-reactive protein (CRP) and matrix metalloproteinase 9 (MMP-9) have been observed among people with periodontitis." (PMID 30873290, 2019). "In the past decade, several epidemiologic studies have been investigated the association of MMP-9 -1562C>T (rs3918242) and MMP-2 -753C>T (rs2285053) polymorphisms with susceptibility to periodontitis." (PMID 31497543, 2019).
periodontitis (continued). "MMP-8, MMP-9, TRAP-5, and MPO demonstrates very high diagnostic accuracy in GCF for discriminating periodontitis, apical periodontitis, gingivitis and/or healthy periodontium, supporting their usefulness for PoC diagnostics." (PMID 31379856, 2019). "Among MMPs, neutrophil-derived MMPs (MMP-8 and MMP-9) have been reported to play major roles in tissue destruction in periodontitis." (PMID 30386502, 2018). "Not only PMN but also macrophages, keratinocytes and osteoclasts are reported to express MMP-9 in periodontitis lesions." (PMID 30386502, 2018). "The expression of MMP-9 as a periodontitis marker was significantly increased in the LPS groups compared to the PBS groups." (PMID 30246792, 2018). "The sensor is sensitive also to cleavages by MMP-1, MMP-13, and MMP-9 present and upregulated in the diseased periodontitis and peri-implantitis tissue and oral fluids." (PMID 30154936, 2018). "Because type I collagen represents the bulk component of periodontal extracellular matrix, special attention has been paid to collagenases—particularly MMP-8 and MMP-13- and gelatinases—MMP-2, and MMP-9- in periodontitis." (PMID 28218665, 2017). "A meta-analysis involving in excess of 6000 individuals established that MMP-9-753 C/T polymorphism reduced the risk of chronic periodontitis, while MMP-3-1171 5A/6A and MMP-8-799 C/T polymorphisms increased the risk of chronic periodontitis." (PMID 28218665, 2017). "Selective production of MMP-9 can lead to the acceleration of matrix degradation in pathological conditions, such as periodontitis." (PMID 28847008, 2017). "Cluster 2 genes (n = 12) were positively correlated with the expression of MMP2 and CTSK in both health and periodontitis, as well as with MMP9 only in periodontitis." (PMID 27486459, 2016). "And based on previous studies, dramatically elevated levels of MMP-1, MMP-2, MMP-3, MMP-8, and MMP-9 have been detected in gingival crevicular fluid, peri-implant sulcular fluid, and gingival tissue of periodontitis patients." (PMID 27194818, 2016). "Lastly, since tissue destruction associated with periodontitis is mostly mediated by MMPs, we evaluated the effect of Daiokanzoto on the catalytic activity of MMP-1 and MMP-9, which are secreted by several human cell types." (PMID 26859747, 2016). "Smoking and periodontitis were both associated with increased levels of MMP8 and MMP9 in gingival crevicular fluid in the sense of additional factors." (PMID 26656474, 2015). "Excessive production of MMP-2 and MMP-9 can lead to accelerated matrix degradation in pathological conditions such as periodontitis." (PMID 24819928, 2014). "MMP-2 and MMP-9 have been demonstrated to regulate proteolytic degradation in periodontitis; the effects of PTL on the expression of MMP-2 and MMP-9 in hPDLCs were therefore investigated." (PMID 25610476, 2014). "This study examined the relationship between gingival crevicular fluid (GCF) and serum sclerostin and PGE2 levels and the inflammatory bone resorption associated with chronic apical periodontitis (AP) as well as the correlation between sclerostin regulation and RANKL and MMP-9 levels." (PMID 40323540, 2026). "In our analysis, MR findings revealed associations of MMP‐9 and TNF with periodontitis." (PMID 40913361, 2026). "Considering that high levels of MMP-9 may be related to IL-1α, TNF-α, and bacterial LPS stimulation, the measurement of GCF MMP-9 levels has been suggested as a means of monitoring chronic apical periodontitis." (PMID 40323540, 2026). "Clinical trials in periodontitis, rosacea, and vascular inflammation consistently demonstrate reduced gingival crevicular fluid or plasma MMP-9, improved tissue stability, and lower inflammatory indices when sub-antimicrobial dose doxycycline (SDD) is added to standard care." (PMID 41304763, 2025). "The gelatinase MMP-9 also plays an important role in periodontitis." (PMID 41002732, 2025).